GJB2 (gap junction protein beta 2)
Diseases named in the same sentence as GJB2 in open-access papers (continued):
Sharing a sentence is not in itself a finding about the gene and the disease.
deafness (continued). "On the other hand, two dominant and a series of recessive mutations in 11 deafness-associated genes were also identified as the independent pathogenic causes in 13 additional probands, suggesting that those probands are co-incidental carriers of the GJB2 mutations." (PMID 31992338, 2020). "Additionally, a cohort of 180 Cameroonians with non-syndromic deafness of either putative genetic origin or unknown origin were screened for GJB2 mutations in 2014." (PMID 32098311, 2020). "Gjb6 has also been linked to human deafness, although the deleterious effects of Gjb6 knockdown in mice are less severe than those of Gjb2 and may be partly caused by associated downregulation of Gjb2." (PMID 29073148, 2017). "Thus, deafness-causing variants in the genes underlying Connexin-related deafness (GJB2 and GJB6, also sometimes referred to as Connexin-26 and Connexin-30, respectively) appear to play a significant role in the history and formation of the Deaf community and Deaf culture in the United States." (PMID 25375116, 2014). "However, in East Asian populations, GJB2 is responsible for a much lower percentage of deafness cases, and other genes associated with this disease remain largely unknown." (PMID 23865914, 2013). "Successful in vivo gene-therapy trials for OTOF-related deafness have demonstrated that restoring auditory function in humans is achievable, yet there are no current corrective therapeutic options for the treatment of GJB2-related deafness." (PMID 41516362, 2026). "This review integrates molecular, clinical, and translational data to provide an updated understanding of GJB2-related deafness and its emerging treatment landscape." (PMID 41516362, 2026). "Together, these scientific and clinical advancements represent a paradigm shift from supportive to disease-modifying precision therapy for GJB2-related deafness." (PMID 41516362, 2026). "The GJB2 gene (GenBank M86849, MIM 121011) encodes connexin 26 (Cx26), a gap junction protein that was first identified as a deafness gene in 1997." (PMID 41516362, 2026). "The phenotypes of GJB2-related deafness are diverse, encompassing both syndromic and non-syndromic forms, with many locations being quite common." (PMID 40336802, 2025). "Future research should continue to unravel the intricate interplay between genetic variants and environmental factors to further advance our knowledge and treatment options for GJB2-related deafness." (PMID 40336802, 2025). "We summarized previous reports related to the GJB2 c.551G>A (p.R184Q) locus, finding a total of 9 publications covering 20 patients, of which only one was diagnosed with syndromic deafness." (PMID 40336802, 2025). "Although we do not know the specific mechanism by which DEX counteracts OHC death, it suggests that it is a viable method for rescuing Gjb2‐related deafness based on protecting OHC death." (PMID 39739601, 2025). "Common causes of deafness in SCs include mutations in genes encoding gap junction proteins, such as GJB2 (Connexin 26), GJB6 (Connexin 30), and GJB3 (Connexin 31)." (PMID 39722701, 2024). "In the present study, 2D-PCR was used to detect the GJB2, SLC26A4, GJB3, and MT-RNR1 genes in 116 deaf patients and to explore the diagnosis rate and mutation patterns of four common pathogenic genes for deafness in Changzhou, Jiangsu, China." (PMID 38172427, 2024). "Among these, a PCR hybridization screening group of 8276 neonates was tested for four deafness genes: GJB2, SLC26A4, mtDNA, and GJB3 by PCR hybridization." (PMID 38172182, 2024). "In this study, we conducted a screening of four common deafness genes (GJB2, GJB3, mitochondrial MT-RNR1, and SLC26A4) in the Chinese population to exclude mutations in these commonly associated deafness gene loci." (PMID 39020321, 2024). "These mice serve as a valuable tool for studying the role of connexin 26 in the cochlea and are useful for evaluating gene therapy vectors and developing therapies for GJB2-related deafness." (PMID 38525683, 2024).
deafness (continued). "Despite the genetic heterogeneity, some genes showed greater contribution to cases of autosomal recessive deafness in our study: GJB2, CDH23 (10.34%), MYO15A (7%), OTOF (7%), and USH2A (7%)." (PMID 39498320, 2024). "The GJB2 gene is most commonly responsible for HL worldwide, accounting for up to 50% of nonsyndromic deafness." (PMID 37106706, 2023). "The GJB2 and SLC26A4 genes were the most common deafness susceptibility genes and their mutations accounted for 28.5% [GJB2: 16.6% (71/428), SLC26A4: 11.9% (51/428)] of mutation positive patients in our study." (PMID 36597107, 2023). "Thus, the mouse models developed here of homozygous 35delG mutations in Gjb2 might completely mimic human hereditary deafness and might lead to the identification of pathogenic mechanisms and might provide a good system for testing treatments such as gene therapy." (PMID 37178259, 2023). "From an epidemiological perspective, GJB2 and SLC26A4 mutations were involved in 28.5% of cases of deafness with a gene variant, while the remaining cases arose from rare gene mutations." (PMID 36597107, 2023). "Carrier screening for common deafness genes in the Chinese population, including the GJB2 and SLC26A4 genes, was performed using next-generation sequencing technology." (PMID 38274112, 2023). "In conclusion, this study performed preconception or prenatal carrier screening for the common deafness genes GJB2 and SLC26A4 in 9,993 individuals from China, showing carrier frequencies of 2.86% and 2.63%, respectively." (PMID 38274112, 2023). "In this study, preconception or prenatal carrier screening for the deafness genes GJB2 and SLC26A4 was performed in 9,993 individuals from China, with frequencies of 2.86% and 2.63%, respectively." (PMID 38274112, 2023). "In terms of nearby genes—including the deafness- and cataract-associated connexins (GJA3, GJB2, and GJB6) —we found significantly reduced expression of only GJB6 (log2fc = −1.06, p = 3.47 × 10−4)." (PMID 37239394, 2023). "After genetic counseling, her spouse chose to undergo sequencing for the target genes (GJB2 and ATP7B), namely, GJB2: c.109G > A (p.Val37Ile), was detected, which usually leads to autosomal recessive hereditary deafness." (PMID 37031186, 2023). "We still lack direct evidence that cochlear inflammation leads to Gjb2-related cochlear sensory epithelial injury and deafness." (PMID 35688810, 2022). "Other diseases appear more frequently in Brazilians (GJB2-related deafness, one in 5.7 thousand in SABE versus one in 19 thousand in gnomAD and MEFV Familial Mediterranean fever, one in 55 thousand versus one in 353 thousand in gnomAD)." (PMID 35246524, 2022). "Twenty-five genes were present in both male and female hearing difficulty high variant load lists, including seven deafness genes (CLIC5, MYH14, COL9A3, ELMO3, FSCN2, GJB2, SLC26A5)." (PMID 35761239, 2022). "Although we do not know the specific mechanism by which DEX antagonizes OHC death, it indicated that it is a feasible method to save Gjb2-related deafness based on protecting OHC death." (PMID 35688810, 2022). "Despite not being direct homologs, expression and mutant analyses have found that zebrafish gjb8 and human GJB2/GJB6 genes are all involved in inner-ear support cell function and loss of these genes in their respective systems causes deafness." (PMID 35325106, 2022). "Here, we propose a stepwise strategy including the detection of common deafness genes with multiplex PCR plus high-throughput sequencing, Sanger sequencing of GJB2 non-coding exon 1, MLPA of the STRC gene, and WES." (PMID 36568381, 2022). "The severity of GJB2-related deafness is widely diverse, even among siblings with the same genotype." (PMID 35457072, 2022). "It increased probe coverage density for 29 genes (full-length design for GJB2, SLC26A4, and POU3F4 genes) to facilitate Cap-CNV analysis and detection of deafness-associated genes in mitochondrial loop DNA." (PMID 36350814, 2022).
deafness (continued). "Genetic causes, particularly pathogenic variants in several highly prevalent deafness genes (e.g., SLC26A4, GJB2, MYO15A and OTOF) are associated with favorable CI outcomes, whereas certain imaging findings such as CND are associated with unfavorable outcomes." (PMID 36009393, 2022). "In general, gene mutations in AR deafness tend to have more LOF mutations; GJB2 (frequency of LOF: 76.7%), STRC (97.2%), MYO15A (44.8%), LOXHD1 (71.4%), USH2A (64.9%), and PCDH15 (75.0%)." (PMID 34599366, 2022). "Because large deletions in the GJB2 or GJB6 gene exhibit a digenic mode of inheritance in the induction of deafness in humans, double Cx26+/−/Cx30+/− heterozygous mice have been established for mechanism research." (PMID 35457072, 2022). "To further verify the effectiveness of DEX in treating Gjb2-related deafness, we established a targeted DC Cx26-null model with both OHC death and deafness." (PMID 35688810, 2022). "In China, GJB2 c.[235delC] + [235delC] homozygotes were the most common, which accounted for 55.10% of GJB2 gene-related deafness, followed by 235delC heterozygote (20.40%), and 235delC/299-300delAT compound heterozygote (10.2%)." (PMID 34276761, 2021). "The coding sequence adjacent to the exon 2 regions of GJB2 gene for 63 patients with recessive hereditary deafness was performed, in which two frame changes and four wrong mutations were recognized in nine Iraqi patients." (PMID 33912482, 2021). "Approximately 4–17% of deafness in patients in China is caused by SLC26A4 variants, followed by the GJB2 gene." (PMID 34276761, 2021). "Our results are also consistent with the previously published data which suggests that GJB2 sequence variations are the primary contributor of deafness in Pakistani individuals." (PMID 34695157, 2021). "While some variants are prevalent in certain populations, such as GJB2 167delT in Ashkenazi Jews and TMC1 p.Ser647Phe in Moroccan Jews, many of the deafness genes affect only a handful of families." (PMID 33350593, 2021). "They reported that three SNPs (rs3751385, rs7994748, and rs7329857) related to GJB2 gene and one SNP (rs7333214) related to GJB6 gene showed a significant relationship with deafness (OR>1) and a high risk of ARNSHL (OR=11.7) for rs7329857." (PMID 33912482, 2021). "Two of the affected individuals were homozygous for the variants in genes, GJB2, MPDZ, known to cause recessively inherited hearing loss, while other two affected individuals were heterozygous for a variant in KCNQ4, a dominant deafness-causing genes." (PMID 34946889, 2021). "Further, it would be interesting to see if this advantage exists only for GJB2 variant homozygotes, or if heterozygous carriers for recessive GJB2 deafness would also be resistant to shigellosis." (PMID 33147256, 2020). "To examine the roles of nuclear genes (GJB2, GJB3, GJB6 and TRMU) in the phenotypic manifestation of deafness-associated 12S rRNA mutations, we carried out a mutational screening of these genes in affected matrilineal relatives of three pedigrees." (PMID 32400865, 2020). "Molecular epidemiological studies have found several common deafness genes in Chinese deafness population, such as GJB2, SLC26A4, and mtDNA12SrRNA." (PMID 32684921, 2020). "Mutations in GJB2 and GJB6 cause a wide variety of phenotypes resulting in pre- or post-lingual hearing loss ranging from mild to profound deafness." (PMID 33193034, 2020). "Some key deafness genes mainly express and have functions in SCs, such as GJB2, which affects the SC’s gap junction and is the most common hereditary deafness gene." (PMID 32424232, 2020). "Targeted sequencing of 415 deafness-related genes identified the heterozygous c.481C>T (p.R161C) mutation in SOX10 and the homozygous c.235delC (p.L79Cfs∗3) mutation in GJB2 as separate pathogenic mutations in distinct affected family members." (PMID 32908489, 2020). "Mutations in the connexin GJB2 and GJB6 genes, encoding respectively CX26 and CX30, cause syndromic and non-syndromic deafness." (PMID 32098144, 2020).
deafness (continued). "Firstly, four common deafness‐related genes (GJB2, GJB3, SLC26A4, and mtDNA 12S rRNA) were evaluated for mutations using a microarray kit." (PMID 31250571, 2019). "Three major deafness‐related genes (GJB2, SLC26A4 (PDS), and mtDNA 12S rRNA) of all individuals enrolled were analyzed by Sanger sequencing." (PMID 30693673, 2019). "We report 4 prelingually deaf children (mean age = 10.5; SD = 1.08), affected by a genetically determined bilateral deafness, due to GJB2 gene mutation Cx26." (PMID 31871493, 2019). "This region is located between GJB2 and GJB6, two prominent deafness genes, where GJB2 is associated with approximately 30–50% of cases of deafness." (PMID 30478432, 2018). "In our previous study, MYO15A pathogenic variant was reported at a frequency of 2.1% in nonsyndromic autosomal recessive deafness, which was the fourth most common deafness gene in Korea, following SLC26A4, GJB2 and CDH23." (PMID 29482514, 2018). "In conclusion, ACEMg significantly influenced deafness progression in the cochleae of both Gjb2-CKO and Diap3-mice." (PMID 26965868, 2016). "The positive influence of ACEMg on structure and function in Gjb2-CKO ears is especially important considering the prevalence of Cx26 deafness." (PMID 26965868, 2016). "Mutations in the connexin genes GJB2 and GJB6 (encoding CX26 and CX30) result in syndromic and non-syndromic deafness via various mechanisms." (PMID 25381570, 2015). "The p.V37I variation in GJB2 is highly prevalent in East Asian deafness, but there is a controversial relationship between some mutations, including p.V37I(c.109G>A), and the hearing phenotype." (PMID 26061099, 2015). "On the one hand, common deafness-related genes such as GJB2 and SLC26A4 have minimal influence on the integrity of spiral ganglion neurons, leading to the speedy restoration of hearing after cochlear implantation." (PMID 26397989, 2015). "There are significant differences in the clinical picture of two rare autosomal dominant syndromes: keratitis–ichthyosis–deafness (KID) syndrome and hidrotic ectodermal dysplasia (Clouston syndrome), which are caused by GJB2 and GJB6 mutations, respectively." (PMID 25575739, 2015). "After exclusion of GJB2 (the gene most frequently involved in non-syndromic deafness in Mediterranean countries), we performed whole-exome sequencing in one sibling." (PMID 26282398, 2015). "Three common deafness-related genes, GJB2, SLC26A4, and mtDNA12SrRNA, were analyzed using all-exon sequencing." (PMID 26252218, 2015). "The c.109G>A variation in GJB2 is highly prevalent in East Asian deaf patients—11.1% in Thai deafness, 16.5% in Japanese deafness, 19.4% in Korean deafness, and 6.7% in Chinese deafness." (PMID 26061099, 2015). "A preliminary survey of Chinese domestic genetic epidemiology for deafness showed that the GJB2, SLC26A4 and mitochondrial 12S rRNA (MTRNR1) genes are common mutation hot spots in Chinese nonsyndromic hearing loss." (PMID 24348793, 2014). "Of notice, about half of all cases of human deafness in countries surrounding the Mediterranean have been linked to mutations in the GJB2 gene, which encodes Cx26." (PMID 24624091, 2014). "In the present study 53% (16/30) of the families were found to carry causative mutations in GJB2 illustrating that the most frequently involved gene in deafness in the Pakistani population is GJB2 followed by MYO15A (13%, 4/30) and TMC1 (10%, 3/30)." (PMID 24949729, 2014). "Many deafness genes, including the well-known deafness genes GJB2 (MIM#121011), SLC26A4 (MIM#605646) and 12S rRNA (MIM#561000), have been identified." (PMID 25474651, 2014). "Connexin 26, a gap junction protein encoded by the GJB2 gene, is the most common molecular defect in nonsyndromic autosomal recessive deafness in China." (PMID 24341454, 2013).
deafness (continued). "GJB2 gene mutations, GJB6 deletion, and the A1555G mitochondrial mutation play a major role worldwide in causing deafness, but there is a high degree of genetic heterogeneity and many genes involved in deafness have not yet been identified." (PMID 24312468, 2013). "Variants detected by targeted next generation sequencing of 82 deafness genes from two subjects (SH42-94, SB51-95) carrying p.V37I variant of GJB2." (PMID 23637863, 2013). "GJB2, SLC26A4 and mitochondrial DNA (mtDNA) 12S rRNA are thought to be the most common causes of nonsyndromic autosomal recessive deafness in Asian people." (PMID 24341454, 2013). "Common mutations, such as c.35delG or c.235delC in GJB2 or p.H723R in the SLC26A4 gene, have been reported in many recessive deafness genes, and usually they are population-specific." (PMID 22899989, 2012). "Five prominent deafness-related genes, GJB2, SLC26A4, GJB6, POU3F4, and mtDNA 12S rRNA, were analyzed." (PMID 22389666, 2012). "As a major sensorineural deafness-associated gene that is discovered following the identification of GJB2, SLC26A4 mutation is associated with the dilation of vestibular aqueduct in NSD and accounts for 4-15% of inherited deafness cases." (PMID 21917135, 2011). "Together with GJB2 (23/135), SLC26A4 are the two most commonly mutated genes causing deafness in this region." (PMID 19040761, 2008). "GJB2 gene contribution in deafness among Altaians (8.3%) is mainly defined by the recessive mutation 235delC (6.67%)." (PMID 15790391, 2005). "We found an Asian-specific GJB2 diversity among Altaians, and different GJB2 contribution for deafness in the Altaian and Russian patients." (PMID 15790391, 2005). "In this study we found an Asian-specific GJB2 diversity among the Altaians and different GJB2 contribution for deafness in the Altaian and Russian patients." (PMID 15790391, 2005). "In summary, therapeutics for GJB2-related deafness are poised to emerge in the near future." (PMID 41516362, 2026). "The frequency of deafness gene variants in descending order was SLC26A4, GJB2, GJB3, and 12S rRNA." (PMID 41181184, 2025). "GJB2 is the most common gene responsible for deafness in Chinese newborns." (PMID 40336802, 2025). "Whether environmental factors exacerbate GJB2-related deafness requires further validation in the future." (PMID 40336802, 2025). "Moreover, the skin phenotype in individuals with dominant syndromic deafness related to GJB2 varies in severity among different individuals." (PMID 40336802, 2025). "Therefore, the GJB2 c.235delC, c.299_300delAT, and c.176-191del16 loci can be used as the focus of genetic screening for deafness in Changzhou to avoid blind screening." (PMID 38172427, 2024). "However, in 20 patients (66.6%), the genetic testing revealed a different diagnosis, such as neurodevelopmental disorders (e.g., ZSWIM6-related disorder), deafness (GJB2-related), or Lowe syndrome (OCRL-related)." (PMID 38818036, 2024). "Sanger sequencing of the GJB2 gene, the most common gene related to deafness, showed an absence of mutations in the affected individuals." (PMID 38790217, 2024). "The cell-specific knockout strategy is also a common way to study Gjb2-related deafness." (PMID 35457072, 2022). "However, the expression of cytokines and chemokines in the inner ear of Gjb2-related hereditary deafness is significantly different from that of other types of deafness." (PMID 35688810, 2022). "GJB2-related deafness is congenital or delayed and is mild to profound." (PMID 35457072, 2022). "However, the majority of GJB2 positive cases originated from the same region (Eastern Region) where the village with a high prevalence of deafness (Adamorobe) is located." (PMID 35440622, 2022). "No biallelic pathogenic variants were identified in GJB2, a common cause of deafness in many populations." (PMID 34837038, 2022). "The most readily understandable example is GJB2, the most common deafness gene." (PMID 34599366, 2022).